LEP (leptin)
Diseases named in the same sentence as LEP in open-access papers (continued):
Sharing a sentence is not in itself a finding about the gene and the disease.
Obesity (continued). "Recent studies have shown that diabetes, obesity and elevated levels of CRP, TNF-alpha and leptin are closely associated." (PMID 34923973, 2021). "Because leptin reduces food intake and body weight, the coexistence of high serum leptin concentrations and obesity is widely interpreted as evidence of an attenuation of leptin signaling termed “leptin resistance”." (PMID 33804765, 2021). "Further data should be reviewed regarding the role of leptin in inflammation, and the role of inflammation in the development of leptin resistance and obesity." (PMID 34446063, 2021). "Four proteins were found to associate with the BMI-difference among the T2D patients, as exemplified by the famous obesity marker leptin." (PMID 33941778, 2021). "In fact, regardless of fasting or satiety conditions, individuals with obesity exhibit elevated level of leptin due to a reduced sensitivity to leptin signaling (i.e., leptin resistance), with important physiological implications." (PMID 34173157, 2021). "Hypothalamic inflammation effectively contributes to leptin resistance and subsequent obesity development." (PMID 34526895, 2021). "In this regard, understanding the pathogenesis of obesity-related disorders and the regulation of energy homeostasis by leptin should provide new alternatives in obesity treatment." (PMID 34084149, 2021). "Owing to its higher serum concentration in obesity, leptin is one of the most studied adipokines in the progression and metastasis of breast cancer." (PMID 34588926, 2021). "It plays an important role in glucose and lipid metabolism, is inversely related to leptin, and low levels are observed in obesity, type 2 diabetes, and metabolic syndrome in adults." (PMID 33669328, 2021). "If other biomarkers of stress are routinely used, leptin should be more studied because of its impact on appetite, obesity genesis, and reproductive function." (PMID 34684349, 2021). "In specific, adiponectin expression is enhanced in lean individuals, while leptin expression increases with obesity." (PMID 34422722, 2021). "Leptin and adiponectin production is altered during obesity and these adipokines have been largely reported to modulate NK cell activities." (PMID 35095876, 2021). "In obese and lean individuals, it is secreted following a similar pulsatile pattern, but in obesity, it is proven to have higher pulse amplitudes; therefore, obese children have higher leptin plasma levels, compared with normal-weight subjects." (PMID 34199040, 2021). "For example, the obesity-related adipokine leptin protects against IRI in various tissues including gut, kidney, brain and heart in which leptin activates both RISK and SAFE pathways." (PMID 34642818, 2021). "This literature review aimed at reviewing recent publications on the role of obesity, leptin, and microRNA deregulation in adverse prognosis of breast cancer." (PMID 33482868, 2021). "A key protein of interest in this field is leptin, a peptide hormone that is overexpressed in obesity." (PMID 34912237, 2021). "Periodontitis and overweight or obesity independently change serum levels of leptin, adiponectin, and C-reactive protein (CRP)." (PMID 33603787, 2021). "The depletion of α-MSH in Pomc-null mice resulted in obesity, whereas the blockade of neuronal melanocortin signaling resulted in a decrease in response to centrally administered leptin." (PMID 34440144, 2021). "Subsequently, the selective downregulation of Ob-Rb using lentivirus in ARC promoted diet-induced obesity in rats, demonstrating the ARC region has a role when leptin resistance develops in obesity." (PMID 34084149, 2021). "Previously, promoter methylation of obesity-related genes including LEP, NPY, and LEPR was involved in tumorigenesis of renal cell carcinoma, and LEPR methylation was associated with prognosis, and predicted renal cell carcinoma recurrence." (PMID 33485366, 2021).
Obesity (continued). "An imbalance between energy and material can cause both YangDC and YinDC to a considerable extent in the human body, leading to obesity, which in turn leads to higher leptin values for YangDC and YinDC subjects." (PMID 34055005, 2021). "Firstly, the vicious circle of mutual reinforcing relationship between obesity and insulin and leptin resistance plays an important role in PCOS pathogenesis." (PMID 34122341, 2021). "Recent studies have reported that the level of leptin is not only elevated significantly in the human body with obesity but also increased in the serum and synovial fluid collected from the patients with OA that is correlated with the severity of OA." (PMID 33833854, 2021). "measured miRNAs in whole breast milk that target mRNA of leptin (LEP), adiponectin (ADIPOQ) and their respective receptors (LEPR, ADIPOR1 and ADIPOR2) which are associated with obesity." (PMID 33801634, 2021). "Melatonin was also able to prevent the prooxidant and profibrotic effects of leptin in the cardiovascular system in the context of obesity." (PMID 33800427, 2021). "When leptin concentrations are raised above an individual “threshold” (which is higher in individuals with obesity), the relevant neuronal tracts are less sensitive and further leptin administration evokes little if any response in humans." (PMID 34955895, 2021). "Adipocytes is known to secrete leptin, which is an imperative mark of obesity and is directly proportional to body fat mass." (PMID 34220807, 2021). "In vitro studies of rat LCs showed that leptin at concentrations similar to those reached in obesity inhibited testosterone secretion." (PMID 34940598, 2021). "Increased leptin, which is reported as the product of the obesity gene, contributes to cardiac remodeling through Leptin-Aldosterone-Neprilysin Axis." (PMID 34026868, 2021). "Among them, the simultaneous presence of obesity and arthritis elevated the leptin levels compared to the groups having obesity or arthritis alone." (PMID 34721412, 2021). "We demonstrate an insulin- and leptin-resistant phenotype in IIH in excess of that driven by obesity." (PMID 33848268, 2021). "Rodents with Socs3 deletion in proopiomelanocortin (POMC) neurons are resistant to diet‐induced obesity and have lower levels of circulating leptin." (PMID 34057306, 2021). "Germline ablation of either Kif3a or Tg737 in adult mice resulted in hyperphagia-induced obesity with elevated serum leptin, insulin, and glucose levels." (PMID 34211092, 2021). "After oral administration of extracts rich in polyphenols, also the leptin/adiponectin ratio, an important marker for inflammation and obesity, decreased." (PMID 34444774, 2021). "It has been elucidated that hypothalamic inflammation induced by fatty acids leads to obesity and it can induce insulin and leptin resistance which are involved in the regulation of food intake and obesity." (PMID 34611217, 2021). "Several factors can influence insulin sensitivity such as obesity and fat distribution, age and sex, genetics, exercise, dietary nutrients, and hormones (glucagon, epinephrine, cortisol, leptin, growth hormones, sex hormones, amylin)." (PMID 33467677, 2021). "In obesity, leptin-mediated increases in aldosterone promote sodium retention, increase cardiac filling pressures, exacerbate remodeling, and accelerate the progression of HF." (PMID 33809061, 2021). "In mouse knockout models, leptin resistance precedes the development of obesity, suggesting that dysfunctional satiety sensing leads to obesity in BBS." (PMID 34759842, 2021). "When the offspring were given a high-calorie diet, leptin administration inhibited obesity developmentand reduced the consumption of cookies only in males." (PMID 34782887, 2021). "In obesity, leptin resistance develops, leading to an inability to detect satiety despite sufficient available energy stores." (PMID 33866464, 2021).
Obesity (continued). "In this context, leptin has a proinflammatory capacity, not only with a key role in obesity and food intake, but also in neuroendocrine regulation, reproduction and diseases such as rheumatoid arthritis and other autoimmune diseases." (PMID 34202969, 2021). "Leptin has an essential role in the regulation of reproduction; however, in obesity, increased levels of this adipokine are produced by adipocytes." (PMID 34940598, 2021). "In contrast, in obesity, partial reduction of plasma leptin levels has been suggested to enhance insulin sensitivity." (PMID 34682732, 2021). "Leptin, a 16 kDa protein hormone overexpressed in obesity, is a crucial adipokine that can regulate appetite satiety." (PMID 34350120, 2021). "As such, Rap1 signaling in the CNS has emerged as a crucial mediator for the effects of HFD feeding, including the development of leptin resistance, obesity, and glucose imbalance." (PMID 33974562, 2021). "Some studies, predominantly using radiolabelled leptin, have suggested that altered transport of leptin across the blood brain barrier accounts for the resistance to the metabolic actions of leptin that is characteristic of diet-induced obesity." (PMID 33679451, 2021). "Most studies address leptin as a potential pharmacological therapy in the control of weight gain and obesity." (PMID 34884416, 2021). "A growing body of research indicates that higher serum concentration of leptin and lower adiponectin are correlated with obesity and increased BC mortality rate." (PMID 34503198, 2021). "Although celastrol’s molecular mechanism regulates leptin sensitivity remains obscure, it was found that celastrol mediates leptin sensitization and exerts anti-obesity effects through increasing interleukin-1 receptor 1 (IL1R1) expression in the hypothalamus." (PMID 34084149, 2021). "A one-year follow-up study found increases in Leptin (a hormone that controls appetite which is found in higher levels in women with obesity) in DMPA users compared to copper IUD users in those gaining > 3 kg." (PMID 33898953, 2021). "Obesity is often connected with leptin resistance, where elevated levels of leptin have a poor impact on metabolism." (PMID 34299048, 2021). "In addition, leptin may increase hepatic GH-sensitivity, as suggested by the GH-resistance seen in conditions associated with acute and chronic hypoleptinemia, and the increased GH responsiveness associated with idiopathic, hyperleptinemic obesity." (PMID 34002033, 2021). "Since leptin has been reported to contribute to T cell impairment in obesity, we tested if leptin receptor signaling in T cells was required for ATT dysfunction." (PMID 33724954, 2021). "Inhibition of Kdm6a restores the H3k27me3 modification, reduces the Cry1 expression in the hypothalamus, and sensitizes leptin signaling to combat obesity‐related disease." (PMID 34306972, 2021). "Taken together, our findings suggested that H19-GOF plays important roles in modulating the metabolic balance of skeletal muscles, leading to muscular hypotrophy and resistance to HFD or leptin resistance-induced obesity." (PMID 34454586, 2021). "Leptin also takes part in the development of obesity, and plasma leptin concentration is found to be elevated in obese subjects." (PMID 34407095, 2021). "An inverse correlation between circulating spexin and leptin levels was reported in adolescents with obesity." (PMID 34100896, 2021). "Despite the anti-obesity effects of leptin, obese individuals have elevated serum leptin levels, and administering leptin to obese individuals only produces an extremely limited impact on obesity." (PMID 32886313, 2021). "High leptin levels in aging and obesity upregulate the proinflammatory cytokines IL-6 and TNF-α, reducing insulin-like growth factor 1 (IGF1) activity and decreasing their anabolic actions on skeletal muscle." (PMID 34676021, 2021).
Obesity (continued). "In this study, we have examined the effects of PaPE-1 on metabolic health, in particular, examining its effects on the liver transcriptome and on plasma metabolites in two different mouse models: diet-induced obesity (DIO) and leptin-deficient (ob/ob) mice." (PMID 34684335, 2021). "Most studies have used leptin gene therapy to study its impact on body weight, food consumption and obesity." (PMID 34947993, 2021). "The associations between the polymorphisms in LEP and LEPR genes and human obesity are still controversial." (PMID 34205732, 2021). "On account of Celastrol, a small molecule extracted from the roots of Thunder of God Vine plant and found to act as a sensitization of leptin through CMAP, leptin combined with it can be used to treat obesity with leptin deficiency." (PMID 33776757, 2021). "Leptin is known to increase in people with obesity as it is produced by adipose tissue, and the circulating concentration of leptin is positively affected by body fat stores." (PMID 34257764, 2021). "Increased leptin in people with obesity enhanced responsiveness to endotoxin, and activated STAT3 signaling through CD14, which is co-receptor of TLR4." (PMID 33923817, 2021). "Another factor produced by adipose tissue that has overlapping roles in obesity, insulin resistance, and hypertension is leptin." (PMID 34966295, 2021). "Another potential therapy candidate to prevent obesity-related vaccine failure is represented by chemical chaperones that, by decreasing ER stress induced by obesity, can improve leptin sensitivity." (PMID 33804765, 2021). "Future studies with a more substantial sample size within each BMI category (especially obesity which was rare in our study) should specifically evaluate this effect modification of leptin by early-pregnancy BMI." (PMID 34615489, 2021). "High plasma leptin in subjects with obesity, along with CXCL-10 and TNF-α, is a predictor of COVID-19 severity and disease progression." (PMID 34373739, 2021). "CNS infection → Hypothalamic inflammation, neurotransmitter imbalance (GABA predominance), obesity, and leptin resistance." (PMID 34795562, 2021). "Adipose tissue is an important source of adipokines, such as pro-inflammatory leptin, produced in excess in obesity, and adiponectin with anti-inflammatory effects with reduced synthesis." (PMID 33418879, 2021). "In vivo studies have demonstrated that whole-brain deletion of PTP1B resulted in leanness, hypersensitivity to leptin, and resistance to HFD-induced obesity, a phenotype partly associated with increased hypothalamic activation of STAT3." (PMID 34201257, 2021). "Several mechanisms have been proposed to explain the association between obesity and increased risk of CRC, including the insulin-like growth factor system, adipokines (eg, leptin, adiponectin), oxidative stress, and steroid hormones." (PMID 33442661, 2021). "Leptin therapy has been approved for hypothalamic amenorrhea, partial lipodystrophy, diabetes, neurodegenerative diseases, depression, and common obesity where plasma leptin levels are relatively low." (PMID 34638947, 2021). "Other SNPs within the LEPR are associated with a higher BMI in a Korean or Spanish population, insulin resistance or adiponectin serum level, as well as obesity and leptin serum level." (PMID 33922961, 2021). "Accumulating studies have shown that leptin has a certain impact on the growth of ovarian cancer, which provides a direct link between obesity and the progression of ovarian cancer." (PMID 34485124, 2021). "As expected, all indices of adiposity (body mass index (BMI), waist circumference, body fat percentage and serum leptin levels) were higher (p < 0.0001) in participants with severe obesity compared with normal-weight controls." (PMID 34884755, 2021).
Obesity (continued). "This review highlights the distinctive facts regarding the link between obesity and inflammation, specifically the interplay of leptin and inflammatory cytokine response leading severity and mortality among COVID-19 patients." (PMID 34220807, 2021). "Reduced sympathetic responsiveness to leptin variations suggested that peripheral leptin resistance was present in women with obesity." (PMID 34884416, 2021). "In six of them, a slightly increased frequency of overweight or obesity was observed in adults with LEP wt/- vs wt/wt." (PMID 34448070, 2021). "Leptin, an important secretory product of adipocytes that is increased in obesity, has important proinflammatory actions on the secretion of cytokines (TNFα, IL-1, IL-6) and on innate and adaptive immune cells." (PMID 34359821, 2021). "Among the diverse adipokines, leptin has been acknowledged as a key candidate molecule linking obesity and BC, due to its vicious function in obese-related BC growth and metastasis." (PMID 34350120, 2021). "Ozcan and colleagues identified the natural compound celastrol as a potential leptin sensitizer and anti-obesity agent." (PMID 34084149, 2021). "Another particular adipokine, resistin, was shown not only to be increased in circulation during obesity, but also to synergize with leptin on SOCS3 upregulation in various tissues." (PMID 33924072, 2021). "This short-term meal-associated endocrine regulation of energy balance is disrupted in obesity by development of resistance of peripheral tissues to both insulin and leptin." (PMID 34836068, 2021). "To further gauge the effects of HSG4112 on obesity, we investigated the expression levels of genes related to energy metabolism, leptin and insulin signaling, and inflammation." (PMID 32943760, 2021). "Leptin is involved in the regulation of food intake and energy homeostasis, and its level is elevated in the presence of obesity." (PMID 33513939, 2021). "Leptin exerts its anti-obesity action mainly by targeting ObR-expressing neurons in the hypothalamus in the central nervous system (CNS)." (PMID 34356668, 2021). "Leptin is positively correlated with obesity and positively affects bone mineral density, but the specific mechanism is still unclear." (PMID 34717752, 2021). "While neuroinflammation disrupts insulin sensitivity and leptin resistance, obesity reciprocally impairs microglia function." (PMID 35127598, 2021). "PTP1B also downregulates the signal of leptin, an adipokine that controls food intake and increases energy expenditure and, thus, has a central importance in the global obesity and cardiovascular disease problem." (PMID 34677434, 2021). "This review highlights the importance of a molecular diagnosis of leptin gene expression in severe obesity." (PMID 34504472, 2021). "Recurrent obesity was characterized by enhanced glucose intolerance, elevated serum levels of leptin and low-density lipoprotein (LDL), an increase in total body fat composition, and decreased energy expenditure." (PMID 33498462, 2021). "Another adipokine, leptin, also represents a key molecular mediator in the relationship between obesity and breast cancer." (PMID 34485137, 2021). "A decline of 72% in serum leptin concentration has been observed in individuals with obesity after an acute exposure to total fast (0 kcal, 52 hours)." (PMID 34899599, 2021). "We previously reported that leptin, at concentrations relevant to obesity and diabetes, has a direct stimulatory effect on the proatherogenic matricellular protein, thrombospondin-1 (TSP-1), implicated in atherosclerosis." (PMID 34064112, 2021). "The results demonstrate that an increase in blood leptin levels in pregnant females has asex-specif ic effect on the metabolism of the offspring increasing resistance to obesity only in male offspring." (PMID 34782887, 2021). "Fucoxanthin affects the lipid metabolism through the leptin and adiponectin-mediated pathways for anti-obesity." (PMID 33809062, 2021).